MYC (MYC proto-oncogene, bHLH transcription factor)
Diseases named in the same sentence as MYC in open-access papers (continued):
Sharing a sentence is not in itself a finding about the gene and the disease.
tumor (continued). "Intriguingly, the decrease in directionality induced by oncogenic MYC levels was a powerful stratification for tumor stage in well-characterized MYC-driven tumor entities." (PMID 30928206, 2019). "DLX5 has been shown to stimulate tumor cell proliferation through upregulation of the MYC expression." (PMID 31093489, 2019). "The small isoform of BAG1, BAG1S, in cooperation with the HSP70 chaperone complex, promotes cell survival in MYC overexpressing tumor cells." (PMID 30902071, 2019). "We found that p27Super mice had a dramatic delay in tumor onset compared to the Cks1 knockout alone in both LMP2A/λ-MYC/p27Super mice and λ-MYC/p27Super mice." (PMID 30992353, 2019). "Median tumor-free survival time was 378 days in LMP2A/λ-MYC/p27Super mice compared to 63 in LMP2A/λ-MYC mice, a delay of 315 days." (PMID 30992353, 2019). "Point mutations in BAG1S that selectively disrupt its interaction with HSP70 eliminate the pro-survival function in MYC-expressing tumor cells." (PMID 30902071, 2019). "Myc knockdown in MYC-amplified GSCs after tumor initiation impaired tumor growth, confirming a role for Myc in GBM maintenance/progression." (PMID 31266951, 2019). "In accordance with our above results, Western blot analysis revealed that p‐AKT and c‐MYC expression was decreased in the CPA4 knockdown tumor tissues compared with shCtrl tumor tissues." (PMID 31397502, 2019). "Here, we demonstrate that XPO1 inhibition abrogates MYC protein expression and induces massive tumor cell apoptosis." (PMID 31752970, 2019). "Of clinical relevance, treatment of MYC-expressing tumor cells with a small molecule HSP70 inhibitor phenocopies the loss of BAG1S and selectively triggers the death of cells expressing oncogenic levels of MYC." (PMID 30902071, 2019). "The combined drug treatment drastically abrogated MYC protein expression, decreased tumor cell proliferation, and induced apoptosis." (PMID 31752970, 2019). "We found that 21 genes were overexpressed in the MYC+N1ICD mouse tumours compared to NC lung from control mice (doxycycline-free diet)." (PMID 31114017, 2019). "Whereas triple negative, Genefu subtype (ER−/Her-2−), PAM50.Basal were frequently expressing in tumours with high MYC mRNA and high ATM mRNA expressions (all adjusted p values ≤ 0.01)." (PMID 30746633, 2019). "The small isoform of BAG1, BAG1S, in cooperation with the HSP70 chaperone complex, selectively mediates cell survival in MYC overexpressing tumor cells." (PMID 30902071, 2019). "Recently, DNA copy number analysis revealed frequent genomic amplification of the MYC gene in MPM tumor samples and cell lines." (PMID 31289611, 2019). "Recently, G9a has been demonstrated to interact with several transcriptional factors, including GATA3 and ZEB2, STAT3, and MYC, leading to the repression of gene transcription, while enhancing tumor survival." (PMID 31619200, 2019). "We report here that a single isoform of BAG1, termed BAG1S, is responsible for the survival of tumor cells with elevated MYC." (PMID 30902071, 2019). "The present study was undertaken to identify this effector function and subsequently assess the utility of targeting it to trigger the apoptosis of tumor cells expressing elevated levels of MYC." (PMID 30902071, 2019). "TEAD deregulation affects well-established cancer genes such as KRAS, BRAF, LKB1, NF2, and MYC, and its transcriptional output plays an important role in tumor progression, metastasis, cancer metabolism, immunity, and drug resistance." (PMID 31212916, 2019). "c-MYC, a key transcription factor by binding on enhancer box sequences (E-boxes), is frequently dysregulated and acts as a tumor promoting protein in numerous cancers." (PMID 31496920, 2019). "MYC+N1ICD tumours also displayed a greater catabolism of 13C-glutamine into 13C4-fumarate and -malate (oxidative route) and 13C3- fumarate and –malate." (PMID 31114017, 2019).
tumor (continued). "A probable consequence in MM can arise from the fact that let-7 miRNAs (a family of 9 mature let-7, encoded by 12 different genomic loci) function as a tumor suppressor through regulation of key oncogenes, including MYC and RAS." (PMID 30654527, 2019). "The intratumoral heterogeneity of c-MYC GCN was arbitrarily defined as GCN gain (c-MYC ≥ 4) in tumor cells between 5% and 50%." (PMID 30733532, 2019). "Overexpression of activated NOTCH1 and its downstream target MYC in mouse lung produced tumours that recapitulated the SCC-distinguishing metabolism." (PMID 31114017, 2019). "Robust activation of MYC-associated apoptosis by combined BCL-2/BCL-XL inhibition and AMPK activation suppressed tumor growth, offered survival benefits, and increased the infiltration and activity of immune cells in the tumor tissue." (PMID 30728358, 2019). "MYC is an important gene involved in many important processes of tumor progression and is located next to the PVT1 locus." (PMID 31601234, 2019). "While MYC is rarely mutated in cancer, most tumors are dependent on MYC for cell division and survival, and MYC amplification is necessary for tumor formation in nude mice." (PMID 31652979, 2019). "Its tumor-suppressor function depends on the repression of at least three gene targets, namely: c-MYC, COX2 and ERBB2." (PMID 31416219, 2019). "In our previous studies, posttranslational degradation of p27Kip1 correlated with earlier tumor development in LMP2A/λ-MYC mice, which was partially attenuated by blocking Cks1-dependent p27Kip1 degradation." (PMID 30992353, 2019). "MYC amplification is a recurrent event in many tumors and contributes to tumor development and progression." (PMID 31886273, 2019). "These criteria outline a model that best reflects the complexity of human tumours in vivo, while ensuring that it is possible to identify MYC dependencies." (PMID 31350286, 2019). "In HBC, c-MYC RNA expression is increased in 22–35% of the tumours analysed and protein expression is reported to be increased in up to 70% of all the cases studied." (PMID 31461477, 2019). "In these cases, significant inhibition of tumor growth was observed, which correlated with reduced expression of target proteins, such as c-MYC and BCL-2, in tumors." (PMID 31472685, 2019). "This study provides novel evidence that MYC directly deregulates the expression of TET1 and TET2 in T-ALL to maintain 5mC and 5hmC patterns in a genome-wide fashion, which is associated with tumor cell-specific gene expression." (PMID 31266538, 2019). "FBXW7 has been characterized as a tumor suppressor due to its ability to target several known oncoproteins including MYC, NOTCH, and Cyclin E." (PMID 30647454, 2019). "Concurring with these observations, siRNA-mediated silencing of PVT1 resulted in a reduction in MYC protein levels in different tumor types such as colorectal carcinoma, breast, and ovarian cancer." (PMID 31781490, 2019). "Accordingly, reduction of MYC expression activates mechanisms that inhibit tumor growth, including senescence, as we have seen in our models." (PMID 31293052, 2019). "In our previous study, tumor onset in LMP2A/λ-MYC/Cks1−/− mice was 25 days earlier than that in λ-MYC mice." (PMID 30992353, 2019). "Given its role in these basic cellular functions, the deregulation of c-MYC plays a critical role in carcinogenesis and tumour progression." (PMID 29396413, 2018). "The results from the screen uncovered MYCBP as a target in sensitizing ALK+ NSCLC to crizotinib, implicating the MYC signaling axis as critical in this tumor type." (PMID 29507657, 2018). "CDK suppression using the PAN CDK-inhibitor Purvalanol A is effective in targeting MYC-driven tumors in vitro but cannot alone suppress tumor growth in MYC-overexpressing transgenic animals." (PMID 29511348, 2018). "The effects of MYCMI-6 treatment therefore resemble the effects of MYC depletion by genetic means in mouse tumor models." (PMID 29968736, 2018).
tumor (continued). "MYC genes encode highly homologous helix-loop-helix leucine zipper transcription factors, and MYC overexpression correlates with aggressive tumor behavior and poor prognosis in a wide array of cancers." (PMID 29799508, 2018). "Following this assumption, we model glutamine-addicted tumor cells that cannot survive on glutamine as the sole carbon source, consistent with the behavior of MYC-positive tumor cells." (PMID 30532226, 2018). "CIP2A inhibits the activity of PP2A on MYC and enhance the MYC protein stability in tumor cell, which promotes the consequential proliferation and cancer progression." (PMID 30044786, 2018). "BCL-2 synergizes with MYC in tumor progression, as observed in transgenic mice, and this cooperation seems to involve the capacity of BCL-2 to block MYC-induced apoptosis in lymphoid cells, without affecting the mitogenic function of MYC." (PMID 29747654, 2018). "MYC is a potent activator of oncogenic transcription programs and demonstrated to be required for tumor growth in multiple tumor types." (PMID 29507657, 2018). "This reduction in c-MYC expression has been demonstrated to induce apoptosis in multiple types of tumor cells." (PMID 30312328, 2018). "With this work we identified MYC as a key player in oncogenic reprogramming as it triggers tumor initiation through the modulation of the epigenetic state of enhancers, thereby perturbing cell identity." (PMID 29523784, 2018). "The c-MYC oncogene mediates multiple tumor cell survival pathways and is dysregulated or overexpressed in the majority of human cancers." (PMID 30312328, 2018). "The tumor suppressive role of miR‐451a in HCC is suggested at least partially through targeting MYC (190080), the same regulatory target proposed in HNSCC." (PMID 30209892, 2018). "The iBETs are a class of MYC inhibitors, which have been demonstrated to have great potential to be translated to clinic in several cancer types, including breast cancer." (PMID 30093685, 2018). "We chose the mouse mammary epithelial cell line, NMuMG, because it is known to be regulated by c-MYC expression in tumor aggressiveness and can expand from a single cell, which is essential for the cloning step." (PMID 32161797, 2018). "Previous work revealed a crucial role for NUAK1 in supporting viability of tumour cells specifically when MYC is overexpressed." (PMID 29106388, 2018). "JQ1 was shown to decrease MYC expression, arrest cell cycle progression, and suppress tumor growth in vivo." (PMID 30459933, 2018). "This alteration leads to the proliferation of damaged cells as MYC is an oncogene and facilitates the growth of tumor." (PMID 29892500, 2018). "The superior anti-tumor activity of tubacin was linked to its ability to not only inhibit accumulation of mutant FGFR3, but also to cause robust downregulation of MYC and cyclin D1, and to induce a DNA damage response and apoptosis." (PMID 29423038, 2018). "Treatment with HSP90 inhibitors, 17-AAG or 17-DMAG, was accompanied by downregulation of canonical MYC target genes, decreased tumor cell proliferation, cell cycle arrest, and increased apoptosis and necrosis." (PMID 30453475, 2018). "A mouse model engineered to conditionally express PIK3CA (H1047R) has revealed that focal amplification of either MET or c-MYC was present in tumours which reoccurred after PIK3CA inactivation." (PMID 29374181, 2018). "Inhibition of BET or CDK7 has been used to target MYC-driven tumours in different contexts, as MYC expression in tumours is frequently maintained at a high level by an associated super-enhancer region." (PMID 29759978, 2018). "We finally evaluated the effects of T‐025 in a mouse tumor model with the intent to validate this molecule as a therapy for MYC‐driven tumors." (PMID 29769258, 2018).
tumor (continued). "MiR-145 can function as a suppressor of cellproliferation and tumor metastasis through targetingmultiple oncogenes such as MYC, Kras, IRS-1, SOX2,MUC1, etc., and its expression level has beenshown in several cancer cell lines." (PMID 29633600, 2018). "The effects of short-term (3 week) treatment with IL-12-LNP (n = 20) versus NST-LNP controls (n = 20) on tumor progression in a transgenic mouse model of MYC-driven HCC were measured by magnetic resonance imaging (MRI)." (PMID 30458889, 2018). "Here, the authors show MYC-driven tumor initiation is reliant on cell reprogramming via an epigenetic program which leads to mammary luminal epithelial cells acquiring basal/stem cell-like properties." (PMID 29523784, 2018). "In tumor development, PER1 suppresses expression levels of tumor-related genes including c-MYC gene." (PMID 29570674, 2018). "Of the 19 relapsed/progressive DLBCL, 58% of cases (n = 11) had tissue blocks with sufficient tumour material for MYC‐FISH analysis." (PMID 29083044, 2018). "Recently, a combination treatment of MKC8866 and docetaxel was shown to eliminate MYC driven tumours in a patient-derived xenograft model." (PMID 30248920, 2018). "Inhibition of tumor cell growth in vivo using mouse tumor models has been reported previously for the MYC:MAX inhibitors 10058-F4, KJ-Pyr-9, KSI-3716 and Mycro327,28,61,62." (PMID 29968736, 2018). "FBW7 is considered a tumor suppressor targeting several dominant oncogenes such as c-MYC, CYCLIN E, c-JUN, and NOTCH for proteasomal degradation." (PMID 29880484, 2018). "Further, the inhibition of miR-17 using a LNP delivery of an anti-oligonucleotide in an autochthonous transgenic mouse model of MYC-induced HCC impedes tumor growth." (PMID 29464015, 2018). "JQ1 treatment significantly inhibited tumor growth of sunitinib-sensitive and -resistant ccRCC cells in part through MYC regulation." (PMID 29796168, 2018). "We further examined the effects of anti-miR-17 therapy using MYC-induced HCC tumor derived cell lines." (PMID 29464015, 2018). "The Vk*MYC model aims to overcome these limitations and to approximate the generated mouse tumor to human MM." (PMID 29732008, 2018). "Taking together, we surmise that nimbolide induces CS in P-glycoprotein-overexpressing cells by targeting PTEN and modulating tumor cellular metabolic elements (HIF1α, FoxO1, c- MYC and ROS)." (PMID 30515268, 2018). "More generally, tumor cells overexpressing MYC are highly sensitive to GLS inhibition as they mainly rely on glutamine oxidation to replenish the TCA cycle, even in hypoxic conditions." (PMID 30564554, 2018). "MYC genes, most commonly MYC and MYCN, are frequently amplified in MB and are associated with a poor prognosis and/or tumor recurrence." (PMID 29511348, 2018). "The inactivation of MYC in tumor models results in recruitment of immune cells promoting tumor regression; conversely, the constitutive expression of CD47 and PD-L1 in MYC T-ALL mouse prevented tumor regression even in the absence of MYC." (PMID 29783691, 2018). "While our data have highlighted a relevant crosstalk between eosinophils and Th17 cells in the BM of Vk*MYC mice, other cells within the tumor microenvironment produce IL-17, and also stromal cells respond to IL-17 by producing IL-632." (PMID 30510245, 2018). "MYC-driven triple-negative breast cancer (TNBC) has an increased reliance on FAO for uncontrolled tumor growth." (PMID 29907133, 2018). "Among MYCN amplified High-MKI cases (n = 120), 101 (84.2%) tumors were MYCN protein (+), one (0.8%) tumor was MYC protein (+), 2 tumors (1.7%) were both proteins (+), and 16 tumors (13.3%) were both proteins (−)/(+/−)." (PMID 29464082, 2018).
tumor (continued). "Our results demonstrate that systemic delivery of LNP-encapsulated anti-miR-17 family oligonucleotide significantly delayed tumor progression in a mouse model of MYC-driven HCCs." (PMID 29464015, 2018). "We next performed time course experiments of cells treated with DC-34 to assess tumor cell viability and MYC protein levels." (PMID 30315240, 2018). "As a single agent, we did not observe significant anti-MB efficacy of Vismodegib and cisplatin on tumor growth and/or survival, suggesting MYC-driven MB resistance to this HH inhibitor and chemotherapy which is consistent with our in vitro studies." (PMID 29682173, 2018). "We next addressed if treatment with MYCMI-6, -11 and -14 inhibits tumor cell growth and if this correlates with the MYC status of the cells." (PMID 29968736, 2018). "As discussed, a common element of these models is the rearrangement of MYC gene that drives tumor onset and development." (PMID 29732008, 2018). "Syngeneic mouse models revealed the same effect on tumour growth in mice with an intact immune system, though only in MYC-driven tumours." (PMID 30248920, 2018). "Certain cyclin-dependent kinases (CDKs) are further known to support MYC stabilization in tumor cells." (PMID 29511348, 2018). "This provides support the concept that MYC plays a part on steroid dependent and independent tumor development." (PMID 29523126, 2018). "It is impossible for a tumor to have acquired c-MYC amplification or copy number gain during neoadjuvant chemotherapy if it responded to treatment." (PMID 30420657, 2018). "Pharmacokinetic and pharmacodynamic analysis revealed robust MYC repression at 2, 4 and 8 hr following acute AZD5153 administration, supporting MYC modulation as an on-target anti-tumor mechanism in this model." (PMID 30036377, 2018). "SerumAFP > 400 ng/mL predicted significant tumor enrichment for genescorresponding to MYC target activation, high cellproliferation, poor clinical prognosis, and the S2 sub-class." (PMID 29376136, 2018). "Further validation of the efficacy of MYCMI-6 in MYC-dependent mouse tumor models is needed in the future." (PMID 29968736, 2018). "Oncogenes that drive tumor cell proliferation directly or indirectly lead to metabolic changes; c-MYC and other oncogenes upregulate metabolite transporters and enzymes required for glucose metabolism." (PMID 30450049, 2018). "Mice were euthanized 8 days after injection and bone marrow, spleen and liver contained very high levels of infiltrating tumor cells co-expressing the fluorescent reporters for MYC, AKT and BCLXL." (PMID 29765548, 2018). "The reduction of tumor growth was mediated by synergistic suppression of MYC, to affect apoptotic regulators to markedly promote tumor apoptosis." (PMID 30459933, 2018). "Most recently, the polyamine transport inhibitor Trimer44NMe was used in combination with DFMO in an orthotopic mouse model of pancreatic ductal adenocarcinoma, demonstrating tumor growth inhibition as well as decreased MYC expression." (PMID 29799508, 2018). "It was also shown that the oncogenic NOTCH1/MYC pathway inhibited the expression of tumor suppressor miRNAs, including miR-31, miR-150, and miR-155." (PMID 29435192, 2018). "In this work, we report the central role of MYC in initiating and sustaining a stepwise cell reprogramming process of mammary epithelial cells toward a stem cell-like condition, favoring tumor initiation and progression." (PMID 29523784, 2018). "MYCMI-6 inhibits tumor cell growth in a MYC-dependent manner with IC50 concentrations as low as 0.5 μM, while sparing normal cells." (PMID 29968736, 2018). "Atuveciclib has been shown to inhibit MYC expression, which results in anti-tumor activity in multiple xenograft models." (PMID 30647871, 2018). "Consistent with this, downregulation of MYC with specific siRNAs alone and in combination with cisplatin treatment resulted in reduction of cell proliferation in vitro and tumor growth in a xenograft mouse model." (PMID 29712888, 2018).